EGR1 (early growth response 1)
Diseases named in the same sentence as EGR1 in open-access papers (continued):
Sharing a sentence is not in itself a finding about the gene and the disease.
tumor (continued). "Additionally, Egr-1 has been shown to have a role in inhibiting tumor invasion and metastasis across various types of cancers." (PMID 37046823, 2023). "In terms of tumor regulation, EGR1 promotes tumor progression by improving the growth and reproduction ability, as well as migration and invasion ability, of cancer cells in some tumors, but plays a quite opposite role as tumor suppressor in others." (PMID 37188478, 2023). "Next, in the orthotopic xenografts assay, we observed that the restoration of EGR1 rescued the inhibited tumor growth and angiogenesis in PD-L1-silenced tumors, unambiguously demonstrating that EGR1 functions as a necessary regulator of the pro-angiogenic function of nPD-L1." (PMID 36977660, 2023). "In the field of cancer research, EGR1 functioned as both a tumor promoter and a tumor suppressor." (PMID 36932397, 2023). "Recent studies have shown that EGR1 is closely related to the initiation and progression of cancer and may participate in tumor cell proliferation, invasion, metastasis, and tumor angiogenesis." (PMID 36888606, 2023). "Functional verification in our experiments indicated that Egr1 could be a critical factor in the tumor suppressor pathway, capable of activating the downstream gene Gadd45a to induce cell apoptosis." (PMID 38248651, 2023). "STAT3 and EGR1 signaling govern T cell-mediated cell-in-cell tumor formation." (PMID 36124553, 2022). "However, in certain circumstance such as hypoxic microenvironments, the increase in EGR1 expression maintains tumor cell survival, proliferation, metastasis, and tumor angiogenesis." (PMID 35883603, 2022). "Similarly, EGR1 is known to act as a tumor suppressor by regulating growth and differentiation, as evidenced by a complete senescence bypass and the immortalization of EGR1-null mouse embryonic fibroblasts." (PMID 35267541, 2022). "Tumor cell–derived FGFBP1 induces FAPα expression in HSCs via the FGF2/FGFR1/ERK1/-2/EGR1 axis." (PMID 35951441, 2022). "Therefore, EGR-1 presented the function of tumor viability suppression and reflected better treatment effects of current chemotherapy for ESCC." (PMID 36233659, 2022). "EGR1 may suppress tumor effects in breast tumors 15, rhabdomyosarcoma 16 and bladder tumors 17, while promoting tumor effects in prostate cancer 18 and lung cancer." (PMID 35069903, 2022). "EGR1 expression in the tumor microenvironment has been also proven to inhibit tumor growth." (PMID 35923847, 2022). "In addition to its involvement in neuropsychiatric disorders, EGR1 has also been widely examined in the field of cancer where it plays paradoxical roles as a tumor suppressor gene or oncogene." (PMID 36338037, 2022). "As a tumor-inhibitor factor, EGR1 exhibited a dysregulated level in several types of tumors." (PMID 36046377, 2022). "EGR-1 also plays a role in the systemic dissemination of tumor cells." (PMID 35205812, 2022). "Higher mRNA levels of ACAP2, ECHDC3, EGR1, and CD74 were highly associated with tumor development." (PMID 35999505, 2022). "The Egr-1 could play an important role as a tumor suppressor as well as influencing the chemotherapeutic effects." (PMID 36207572, 2022). "The activation of the ERK signaling pathway may stimulate tumor cell proliferation through its ability to initiate the expression of crucial growth-stimulating genes, such as cyclin D1 and early growth response-1 (EGR-1)." (PMID 35764974, 2022). "Analysis of certain human tumor cells and tissues indicate that Egr-1 acts as a tumor suppressor." (PMID 36207572, 2022). "The experimental results of this article confirm our hypothesis and provide a possible tumor suppressor mechanism of EGR-1." (PMID 36233659, 2022). "Depending on the type of tumor, EGR1 can either play an inhibitory role or an activating role." (PMID 36046377, 2022). "However, other reports have indicated that miR-181a is downregulated in HCC and plays a tumor suppressor role targeting cMet, Egr1, and TGF-β." (PMID 36421826, 2022).
tumor (continued). "Low EGR1 expression in PTC is significantly associated with several clinicopathological parameters including male gender, tumor size, and lymph node metastasis, suggesting the novel role of EGR1 as a tumor suppressor in PTC." (PMID 33477921, 2021). "The expression of EGR1 was significantly higher in normal samples compared to tumor samples." (PMID 33477921, 2021). "This review article summarizes possible mechanisms of action of EGR1 in tumorigenesis and tumor progression and may serve as a reference for clinical efficacy predictions and for the discovery of new therapeutic targets." (PMID 33842351, 2021). "Various authors have shown that high EGR1 expression may increase the proliferation of specific types of tumor cells by affecting the cell cycle." (PMID 33842351, 2021). "Therefore, EGR1 performs important functions in tumor cell proliferation, angiogenesis, invasion, and immune responses." (PMID 33842351, 2021). "EGR1 can function as a tumor suppressor or an oncogene, depending on the type of tumor cell." (PMID 33477921, 2021). "It has been reported that EGR1 played an essential role in the development of tumor diseases." (PMID 34889888, 2021). "Another study found decreased expression of cyclin B1, CDC2, p-CDC2, and CDC25C, which may be due to SFN-induced upregulation of the tumor-suppressor gene Egr1 in various breast cancer cells." (PMID 34638282, 2021). "Lower expression of EGR1 was detected in four tumor samples relative to normal tissue." (PMID 33477921, 2021). "Recent studies have shown that EGR1 is closely related to the initiation and progression of cancer and may participate in tumor cell proliferation, invasion, and metastasis and in tumor angiogenesis." (PMID 33842351, 2021). "Moreover, combined inhibition of both GDF15 and EGR1 in a HNC mouse xenograft model showed significantly decreased tumor volume compared to inhibition of EGR1 or GDF15 alone." (PMID 34681812, 2021). "The purposes of this review are to summarize the roles of EGR1 in tumor cell proliferation, apoptosis, and metastasis and in the tumor microenvironment as well as to discuss the possible signaling pathways in which EGR1 is involved to provide a new perspective on cancer treatment." (PMID 33842351, 2021). "Our findings demonstrate that EGR1 is a potential tumor suppressor that leads to apoptotic cell death in THCA and the EGR1/GADD45α axis could be a good therapeutic target for THCA." (PMID 33477921, 2021). "EGR1 can directly bind to the promoter sequences of a variety of interstitial-space–related genes to start their expression and therefore performs an important function in tumor invasion and metastasis." (PMID 33842351, 2021). "Among these significant genes of IL-4 signaling are CFLAR, ALOX5, PMAIP1, EGR1, NCF2, SLC39A8, and PEG10 which have been reported to be associated with tumor progression or chemotherapy-drug resistance through effecting proliferation and apoptosis in previous studies." (PMID 33506057, 2021). "Meanwhile, EGR1 contributes to tumor metastasis as well, by starting SLUG and SNAIL expression." (PMID 33842351, 2021). "In 114 paired cases, EGR1 was significantly inhibited in tumor tissues." (PMID 34497759, 2021). "EGR1 has been reported to inhibit tumor invasion and metastasis in many tumor types." (PMID 33842351, 2021). "Moreover, combined inhibition of both GDF15 and EGR1 showed significantly decreased tumor volume compared to inhibition of EGR1 or GDF15 alone." (PMID 34681812, 2021). "Also, the percentage of Vegf-a-expressing osteocytes correlates with MM tumor vascularity in vivo, and Fgf23, which is made by Ocys, increases Vegf-a production via autocrine signaling and Egr1 activity." (PMID 33057033, 2020).
tumor (continued). "The finding of a very high fraction of MGMT-methylated tumours having simultaneous high EGR1 expression raises the question whether EGR1 is involved in methylation of the MGMT promoter." (PMID 32518380, 2020). "Moreover, REC8 expression was associated with poor tumor prognosis in patients, which is not only attributed to cell growth and migration caused by REC8 reduction, but also promoted EGR1-mediated EMT." (PMID 32958054, 2020). "Mice with EGR1-KO presented an accelerated tumorigenesis in a two-step skin carcinogenesis study." (PMID 32046751, 2020). "However, there are studies showing anti-tumor activity of EGR1 and its role in suppressing metastasis of cancer cells." (PMID 32784711, 2020). "EGR1 induces the tumor cell apoptosis via upregulating tumor suppressors, NAG-1 and PTEN directly." (PMID 33364499, 2020). "In addition, early growth response gene 1 (EGR1) acts as a double-edged sword in cancer by displaying both tumor promoting and suppressing roles." (PMID 32784711, 2020). "In breast, brain and lung cancers EGR1 acts as a tumor suppressor." (PMID 33425921, 2020). "Furthermore, there were six genes (EGR1, MUC20, MUC3A, NBPF19, NOL4L, and OR4L1) that were simultaneously mutated in the tumor tissues and junction tissues." (PMID 33133167, 2020). "However, Epidermal Growth Factor (EGF) promotes tumor progression even with significant EGR1 upregulation." (PMID 30845713, 2019). "Therefore, miR-183 plays an oncogenic role by targeting two tumor suppressor genes, EGR1 and PTEN and miRNA deregulation is crucial to the development of several types of tumors." (PMID 31752446, 2019). "Lastly, we observed that YYJD enhances EGR1 expression and induces cell death in tumour xenografts." (PMID 31237749, 2019). "EGR1 plays a biological role in tumor cells by regulating the transcription of the heparin enzyme and either an inhibitory or an activation role in different tumor types." (PMID 31844579, 2019). "The downregulation of the N-Myc, Egr1, Sox9 mRNAs and the upregulation of Gadd45b mRNA in tumor-bearing mouse heart could conceivably be important in reducing cardiac growth and differentiation." (PMID 31851697, 2019). "EGR1 regulates the expression of its downstream target genes and may exert different biological effects in different tumours." (PMID 31515938, 2019). "In addition, NAB2 upregulation in EGF-treated FaDu cell diminishes EGR1 transcriptional activity, resulting in the upregulation of Sp1-dependent tumor-promoting genes." (PMID 30845713, 2019). "EGR1 acts under certain conditions as a putative tumor suppressor." (PMID 31261735, 2019). "Therefore, we first sought to uncover how EGR1 permits tumor progression in EGF-treated HNSCC cells." (PMID 30845713, 2019). "Their tumor samples were immunohistochemically examined for the expression of Oct4, Egr1, and OPN." (PMID 31399076, 2019). "Given the observation that YYJD exerts the anti‐tumour effect through EGR1 activation in vitro, its anti‐tumour activity in vivo remains unclear." (PMID 31237749, 2019). "Furthermore, experiments with miR-183 knockdown mice led to significant reductions in tumor migration through the direct promotion of EGR1 expression, regulator of cell migration." (PMID 31752446, 2019).
tumor (continued). "EGR1 is an important transcriptional regulatory factor that regulates cell proliferation, differentiation and cell survival and plays an important role in the processes of tumour growth and differentiation." (PMID 31000722, 2019). "EGR1 has been shown to function as both a tumor suppressor and oncogene in cancer." (PMID 29719592, 2018). "Thus, Egr-1 is thought to act as a crucial regulator of tumor cell death, growth, invasion, and angiogenesis." (PMID 29636841, 2018). "Overexpression of EGR1 decreases tumorigenesis in nude mice and various of human tumor cell lines." (PMID 30319594, 2018). "In certain tumour types EGR1 represses transcription of heparanase, which degrades heparan sulphate proteoglycan chains present in the ECM and basement membranes allowing tumour cells to spread and inducing the release of pro-angiogenic chemokines and growth factors." (PMID 30566430, 2018). "In this work, we show that EGR1 functions as a tumor suppressor in RMS." (PMID 29719592, 2018). "miR-183 has an oncogenic role through the regulation of the tumor-suppressor genes, EGR1 and PTEN." (PMID 29324832, 2018). "Also EGR1 was described to be involved in breast tumorigenesis via transcriptional control of miR-20b, which can function as an oncogene via tumor suppressor targeting." (PMID 28402269, 2017). "Egr1 is demonstrated to act as both a tumor suppressor and a tumor promoter in cancers." (PMID 29607419, 2017). "In some tumor types, EGR-1 promotes growth and induces resistance to apoptosis." (PMID 29216821, 2017). "Accumulating studies suggest Egr1 as a tumor suppressor in HCC." (PMID 29607419, 2017). "EGR1, a transcription factor, controls a variety of important cellular events, such as synaptic plasticity, wound repair, inflammation, growth control, differentiation, apoptosis and tumor progression." (PMID 29246166, 2017). "Early Growth Response 1(EGR1) is a putative tumor suppressor gene located in the CDR." (PMID 28081176, 2017). "Interestingly, they include EGR1, ETV4, ETV5 and FosB that have been associated with EMT and tumour aggressiveness in several cancers." (PMID 28651004, 2017). "Collectively, these studies suggest that inhibiting Egr1 expression or function to increase tumor cells’ sensitivity to chemotherapeutics could be applied as a novel approach for HCC therapy." (PMID 29607419, 2017). "The tumor growth was significantly inhibited in EGR1 siRNA group in both U251 and U251SLC cells." (PMID 29246166, 2017). "EGR1-induced PTEN expression directly inhibits the PI3K/Akt/mTOR pathway in tumor cells." (PMID 27935858, 2017). "Taken together, these studies support an anti-tumor role of Egr1 in HCC." (PMID 29607419, 2017). "While the precise role of EGR1 in cell survival remains unclear, disruption of endogenous levels of EGR1 can either inhibit growth or promote tumor progression." (PMID 29228577, 2017). "Taken together these data demonstrate that Egr1 behaves as a tumor suppressor in CML." (PMID 29050203, 2017). "In addition, EGR-1 is induced by hypoxia and plays a critical role in hypoxia-induced tumor progression, survival, and angiogenesis." (PMID 28758926, 2017). "Interestingly, EGR1 is also considered to be either a tumor-suppressor or tumor-promoter in various cell types." (PMID 25971332, 2015). "Similarly, CD49fhiCD24low tumor cells exhibited significantly lower expression of EGR1 (−20-fold, p = 0.02), glucose transporter 3 (SLC2A3; −50-fold, p = 0.03), and GAPDH (−100-fold, p = 0.01) than benign cell counterparts." (PMID 26316122, 2015). "This was evaluated by assaying TTP and EGR1 expression in normal colon and tumor tissue by qPCR." (PMID 26343742, 2015). "Moreover, expression levels of EGR-1 increase with the degree of malignancy, as measured by the Gleason score of the tumor." (PMID 26110651, 2015).